RN7SL614P (RNA, 7SL, cytoplasmic 614, pseudogene)
Gene: Miscellaneous RNA gene on chromosome 1 (10,616,836 to 10,617,115, forward strand). Ensembl gene ENSG00000243267.
Homologues: Orthologues: chimpanzee Metazoa_SRP (99% identical), macaque Metazoa_SRP (85% identical). Paralogues in human: RN7SL1 (83% identical), RN7SL2 (83% identical), RN7SL3 (81% identical), RN7SL296P (81% identical), RN7SL655P (80% identical), RN7SL478P (79% identical), RN7SL127P (79% identical), RN7SL300P (79% identical), RN7SL711P (79% identical), RN7SL712P (79% identical), RN7SL14P (78% identical), RN7SL186P (78% identical), and 700 more.